CD14 (CD14 molecule)
Diseases named in the same sentence as CD14 in open-access papers (continued):
Sharing a sentence is not in itself a finding about the gene and the disease.
Stroke (continued). "In addition to CD14, MHC-II expression is significantly increased on microglia in the response to stroke and it’s expression on the surface of EVs has been well characterized." (PMID 36721258, 2023). "Immunofluorescence histochemistry confirmed co-expression of CD14 and TMEM119 within the stroke-induced striatum, with no detectable expression of CD14 within the contralateral striatum." (PMID 36721258, 2023). "Using nanoflow cytometry, TMEM119+/CD14+ EVs were directly labelled in the plasma and demonstrate an increase 28-days post-stroke, but not 7-days post-stroke." (PMID 36721258, 2023). "However, we found that CD14, CLU and SAA2 were expressed in the sera of stroke patients at various levels." (PMID 33995275, 2021). "CD163+ expression was more pronounced in CD16+ non-classical and intermediate monocytes, as compared to CD14+ classical subtype, 24 h after stroke." (PMID 34201498, 2021). "The impact of SNPs in CD14 (rs2569190), NF-κΒ (rs28362491), TLR2 (rs5743708), and TLR4 (rs4986790) on the incidence of combined endpoint defined as CV death, death from stroke, MI, and stroke/TIA was evaluated." (PMID 34305452, 2021). "CD14highCD16- classical and CD14highCD16+ intermediate monocytes were significantly increased from 0-7 and 3-16 days after stroke, respectively (p<0.05), whereas CD14 dimCD16high non-classical monocytes were decreased from 0–7 days (p<0.05)." (PMID 23936327, 2013). "In addition, the OR (95%CI) of stroke per SD increase in genetically predicted immune cells was 0.970 (0.952, 0.989) for CD40 on CD14+ CD16+ monocyte, 0.976 (0.962, 0.990) for CD40 on monocyte and 0.969 (0.948, 0.990) for CD40 on CD14+ CD16- monocyte." (PMID 38887301, 2024). "At 4 weeks post-stroke, the top 10 gene products in the PPI network were Cd44 (degree = 17), C1qb (degree = 15), Fcgr2b (degree = 14), Spp1 (degree = 12), Cd74 (degree = 12), C4a (degree = 12), C1qa (degree = 12), C3 (degree = 10), Cd14 (degree = 10), and Itgb2 (degree = 10)." (PMID 31888302, 2019). "In the present study, we found that CD14 dimCD16high non-classical Mo had a positive correlation with serum IL-17A from 12–16 days after stroke, suggesting that CD16+ monocytes producing IL-17 have a role in the pathogenesis of brain ischemia after the acute phase." (PMID 23936327, 2013). "In a recent clinical study, we reported a significant elevation of the percentage of CD14++/CD16+ intermediate and CD14+/CD16+ non-classical monocyte subsets, as well as their relative expression of the cannabinoid receptor-2 (CB2), 24 and 48 h after stroke." (PMID 34201498, 2021). "The percentage of CD16+ cells expressing CD163 (median = 16.01%, IQR = 14.05–18.12) was higher (p < 0.01) than the percentage of CD14++ cells expressing this surface molecule (median = 12.46%, IQR = 11.88–14.63) 24 h after stroke, but not at a later time-point (i.e., 48 h after the insult)." (PMID 34201498, 2021).
latent infection (24 papers, 2012 to 2025). "As reported in CD34+ latent infection, the CD14+ latency-associated secretome also suppressed the anti-viral activity of stimulated CD4+ T cells." (PMID 33912186, 2021). "Hence these data show that there are common transcripts associated with HCMV latent infection in both CD14 (+) and CD34 (+) cells, including two lncRNAs and mRNAs that encode UL84 and UL44." (PMID 23717203, 2013). "We also showed that those levels increase during viral reactivation in an HCMV latent infection model in CD14+ cells." (PMID 40284944, 2025). "To investigate the protective function of β2.7 during latent infection, we mock infected, or infected CD14+ monocytes with wild type (WT) virus or virus with a β2.7 gene deletion (Δβ2.7) in the Toledo strain of HCMV." (PMID 35215840, 2022). "A short-term model of latent infection in CD14+ monocytes revealed secretion of inflammatory immune mediators and promotion of differentiation to a macrophage-like phenotype." (PMID 33912186, 2021). "Here, we have shown that experimental latent infection of CD14+ monocytes, an established in vitro model system for latent infection in vivo, also results in changes to the cellular secretome causing upregulation of cIL-10, CCL8 and, in particular, CXCL10." (PMID 33912186, 2021). "We have analyzed the effect of HCMV latent infection on the secretome of CD14+ monocytes, identifying an upregulation of both CCL8 and CXCL10 chemokines in the CD14+ latency-associated secretome." (PMID 33912186, 2021). "This is supported by a recent report showing that interferon induced genes are downregulated during latent infection of CD14+ monocytes." (PMID 31967545, 2020). "Recently, we reported an analysis of total latency-associated changes in the cell proteome of latently infected CD14+ monocytes using Tandem Mass Tag technology and identified robust changes in cellular proteins resulting from latent infection." (PMID 31569051, 2019). "Taken together, these data argue that latent infection of CD14+ monocytes results in increased levels of cellular HCLS1, which stabilizes actin filaments and concomitantly results in enhanced monocyte motility." (PMID 31569051, 2019). "Here, we confirm this important function of US28 during latent infection in CD14+ monocytes and, in part, solve this paradox by showing that US28 appears to have very different effects on cell signaling in undifferentiated and differentiated cells." (PMID 29208743, 2017). "First, it was shown the H3K27 methyltransferase EZH2 was recruited to the major IE promoter (MIEP) in CD14+ monocytes where hCMV establishes latent infection in vivo, resulting in increased H3K27Me3 mark at the MIEP region." (PMID 28407004, 2017). "Particularly important is the observation that CD14+ monocytes can induce latent infection in resting CD4+ T-cells." (PMID 26362311, 2015). "CD14+ monocytes represent DC and macrophage precursors in blood [Reviewed in 25], and were also tested for their ability to establish latent infection in resting CD4+ T-cells." (PMID 26362311, 2015). "Cis and trans acting factors involved in human cytomegalovirus experimental and natural latent infection of CD14 (+) monocytes and CD34 (+) cells." (PMID 24603756, 2014). "Then these viruses were used to establish a latent infection in CD14+ monocytes as evidenced by long term UL138 gene expression in an absence of UL123 expression." (PMID 24945302, 2014). "Data presented here strongly implicates lncRNA4.9 as a targeting factor for suppression of IE gene expression during latent infection in CD14 (+) cells." (PMID 23717203, 2013). "In this report we show that, consistent with the presence of active chromatin, that the TR region of the HCMV genome are depleted of nucleosomes during latent infection of CD14 (+) monocytes." (PMID 23717203, 2013). "The parameters involved in human cytomegalovirus (HCMV) latent infection in CD14 (+) and CD34 (+) cells remain poorly identified." (PMID 23717203, 2013).
latent infection (continued). "To study the HCMV chromosome during latent infection we used the CD14 (+) monocyte experimental model." (PMID 23717203, 2013). "Thus, using an established experimental model of HCMV latent infection in CD14+ monocytes, we have characterized the latency-associated changes in the cell secretome using chemokine and cytokine arrays." (PMID 33912186, 2021). "However, in order for this approach to work, it was important to confirm that US28 protein is expressed and trafficked to the cell surface during latent infection of CD14+ monocytes." (PMID 28148951, 2017). "Hence, RNA4.9 has the potential to function as a regulatory RNA in the context of HCMV latent infection of CD14 (+) monocytes." (PMID 23717203, 2013). "As expected, latent infection of primary CD14+ cells yielded only marginal levels of HCMV DNA." (PMID 23300789, 2012). "Recently, we carried out a total proteomic screen of HCMV latently infected CD14+ monocytes, which we had confirmed were truly latently infected by RNA analysis and virion release assays, and identified proteins that were changed as a result of latent infection." (PMID 31569051, 2019). "CMV establishes latent infection in cells of the hematopoietic lineage, including bone marrow-derived CD34+ hematopoietic progenitor cells and circulating CD14+ monocytes." (PMID 40862616, 2025). "In contrast, latent infection has so far been characterized in cells of the early myeloid lineage, including CD34+ hematopoietic stem and progenitor cells (HSPCs) and CD14+ monocytes in vivo." (PMID 31967545, 2020). "HCMV can establish latent infection in early myeloid lineage cells, including CD34+ progenitor cells and CD14+ monocytes, the former of which comprise the major cell type present in HSCTs." (PMID 31580403, 2019). "Despite this, HCMV is not cleared from the host but persists by establishing a lifelong latent infection in undifferentiated cells of the myeloid lineage (CD34+ haematopoietic progenitor cells and their derivative CD14+ monocytes)." (PMID 31580403, 2019). "CD14 (+) or CD34 (+) cells cultured in vitro can be infected with HCMV clinical strains, resulting in latent infection and efficient reactivation of latent virus." (PMID 23717203, 2013). "HCMV establishes a latent infection in CD34+ progenitor cells and CD14+ monocytes." (PMID 34290252, 2021). "Indeed, the upregulation of cIL-10 during latent infection in both CD34 and CD14 monocytes has been proposed to play an antiapoptotic role in latently infected cells." (PMID 32582563, 2020). "Taken together, these data argue for a requirement for US28 in either establishment or maintenance of latent infection of CD14+ monocytes and show that, in the absence of US28, monocytes undergo full lytic infection." (PMID 29208743, 2017). "Haematopoietic progenitors and CD14+ monocytes are usually non-permissive for lytic gene expression which can lead to the establishment of latent infections." (PMID 28400599, 2017). "CD14+ monocytes were also able to significantly increase the induction of latent infection in non-proliferating cells (p > 0.05)." (PMID 26362311, 2015). "Here, we have shown that the myeloid lineage cells capable of producing latent T-cell infection include subpopulations of blood derived mDC; CD1c+, SLAN+ DC and CD14+ monocytes, and confirmed that pDC are distinct in not generating latent infection." (PMID 26362311, 2015). "Together these data show that only CD1c+mDC, SLAN+ DC and CD14+ monocytes were able to establish post-integration latent infection in non-proliferating CD4+ T-cells, while B-cells and CD141+ mDC were able to establish pre-integration latent infection." (PMID 26362311, 2015). "In contrast, using the Merlin clinical isolate, the lack of UL111A did show a decrease in the establishment of latent infection of CD14+ monocytes, as well as in latently infected CD34+ cells." (PMID 25253336, 2014).
latent infection (continued). "For HCMV latent infection of CD34 (+) cells we harvested RNA at 11 days post infection and the RNA-Seq peak map shows the presence of the same transcripts detected in latently infected CD14 (+) cells (11 day latent)." (PMID 23717203, 2013). "The drastic decrease in UL138 transcript expression in CD14+ cells, which is required for latency establishment in CD34+ HSC, may contribute to the delay in the ability of FIX-ΔLUNA to fully establish a latent infection." (PMID 23300789, 2012). "Therefore, we also examined levels of viral miRNAs in cells infected with UV-inactivated virus to ensure that viral miRNAs identified in latently infected CD34+ cells and CD14+ monocytes were derived from de novo synthesised RNAs during latent infection and not input virion RNA." (PMID 27491954, 2016). "Our data reveal that UL78 is expressed during latent infection in THP-1 and CD14+ cells in the absence of pp65, though UL78 is less abundant than during lytic expression of this protein." (PMID 40862616, 2025). "Total latent infection (no L8) was significantly increased in non-proliferating CD4+ T-cells co-cultured with all mDC subpopulations, CD14+ monocytes and B-cells, when compared to CD4+ T-cells cultured alone (p = 0.03)." (PMID 26362311, 2015). "Having established that infection of CD14+ monocytes with Titan-ΔUS28 for 7 days resulted in a lytic rather than a latent infection, we wanted to rule out the possibility that US28 was simply maintaining a latent infection by actively suppressing myeloid cell differentiation." (PMID 29208743, 2017).
pneumonia (24 papers, 2007 to 2025). An acute, acute and chronic, or chronic inflammation focally or diffusely affecting the lung parenchyma, caused by an infection in one or both of the lungs (by bacteria, viruses, fungi, or mycoplasma.). "More recently, the role of inflammation and inflammatory signaling during Ax-mediated pneumonia in mice was addressed using CD14-deficient mice." (PMID 37255468, 2023). "Elaborating on this notion, previous findings of us and others that CD14 is essential in LPS-induced lung inflammation and pneumonia caused by Acinetobacter baumannii are explained by the predominance of the smooth form of LPS in the inocula." (PMID 20419140, 2010). "CD14-dependent pathways, potentially related to LPS, LBP, and sCD14 concentrations, have been implicated in pneumonia-related inflammation in ARDS." (PMID 40375981, 2025). "Immunofluorescence staining analysis showed that CD11c+ CD14+ DCs were spatially located near CD4+ T cells in the lungs of pneumonia patients." (PMID 40789072, 2025). "We observed that CD14 was significantly lower in pneumonia subjects compared to CHF subjects (p < 0.05)." (PMID 30818785, 2019). "The correlations between severity of illness and CD14++CD16+ expression still existed when only patients with pneumonia were considered with p = 0.047 for APACHE II scores (r = 0.538) and p = 0.049 for SOFA scores (r = 0.515)." (PMID 28446249, 2017). "Analogously, CD14 has proved to be essential for bacterial clearance in a rabbit model of E. coli-induced pneumonia." (PMID 23898465, 2013). "We found that wt mice with untreated S. pneumoniae meningitis lived longer than infected mice with a genetic deletion of TLR2 or CD14 or both TLR2 and CD14." (PMID 17428319, 2007). "In Baladi goats with pneumonia and healthy control group, PCR-DNA sequencing revealed SNPs linked to pneumonia susceptibility and resistance in immunological genes (SLC11A1, CD-14, CCL2, TLR1, TLR7, TLR8, TLR9, defensin, SP110, SPP1, BP1, A2M, ADORA3, CARD15, IRF3, and SCART1)." (PMID 40221769, 2025). "Moreover, the proportion of CD14+ cDC2s in the lungs of pneumonia patients increased by nearly 1.5‐fold compared with healthy controls." (PMID 40789072, 2025). "After 2 days of coculture with h‐MSCs, CD14‐positive human monocytes derived from peripheral blood of patients with MDR‐PA‐induced pneumonia expressed high levels of CD206 significantly, compared to those monocytes derived from healthy people, as determined by MFI (p = .034)." (PMID 33463070, 2021). "We found that patients with pneumonia had lower levels of CD14 than those with CHF." (PMID 30818785, 2019). "A detrimental role of CD14 has been defined in the responses against Streptococcus pneumoniae, a Gram-positive bacterium causing pneumonia, and Burkholederia pseudomallei, a Gram-negative bacterium causing melioidosis." (PMID 23898465, 2013). "Previously, we and others showed that CD14 is an essential receptor in LPS-induced lung inflammation and pneumonia caused by gram-negative bacteria." (PMID 20419140, 2010). "This raises the question of what role CD14 plays during polymicrobial epizootic pneumonia within bighorn sheep, where Mycoplasma ovipneumoniae exposure may cause LPS sensitization, resulting in a severe inflammatory reaction when Pasteurellaceae species translocate into the lower respiratory tract." (PMID 39770861, 2024). "Finally, we explored whether the existence of CD14+ PMNs was universal in other bacterial-induced pneumonia models." (PMID 37705063, 2023). "The immune genes’ mRNA levels in goats (SLC11A1, CD-14, CCL2, TLR1, TLR7, TLR8, TLR9, defensin, SP110, SPP1, BP1, A2M, ADORA3, CARD15, IRF3, and SCART1) varied between the healthy and infected goats with pneumonia." (PMID 40711280, 2025). "The expression levels of CD8a, CD14, CD270 and CD 59 were increased, while CD16 and CTLA4 were decreased compared with patients with pneumonia." (PMID 34841705, 2021).
pneumonia (continued). "Associations of PM2.5, NO2, SO2, and O3 with the log-transformed LDH, total protein, CXCL10, IFN-γ, CD14, and CD62 levels in pleural effusion were determined after adjusting for age, sex, BMI, smoking, and disease category (pneumonia or CHF)." (PMID 30818785, 2019). "Lipoteichonic acid (LTA) from S. pneumonia is able to activate TLR2 and CD14." (PMID 19371402, 2009). "Through PCR-DNA sequencing in Baladi goats with and without pneumonia, SNPs linked to pneumonia susceptibility and resistance were discovered in the immunological (SLC11A1, CD-14, CCL2, TLR1, TLR7, TLR8, TLR9, defensin, SP110, SPP1, BP1, A2M, ADORA3, CARD15, IRF3, and SCART1) genes." (PMID 40711280, 2025). "The levels of immunological genes (SLC11A1, CD-14, CCL2, TLR1, TLR7, TLR8, TLR9, defensin, SP110, SPP1, BP1, A2M, ADORA3, CARD15, IRF3, and SCART1) vary in goats with and without pneumonia." (PMID 40221769, 2025). "Real-time PCR was conducted to quantify the expression levels of immunological markers (SLC11A1, CD-14, CCL2, TLR1, TLR7, TLR8, TLR9, β defensin, SP110, SPP1, BP1, A2M, ADORA3, CARD15, IRF3, and SCART1) in Baladi goats with and without pneumonia resistance." (PMID 36977224, 2023).